BCAT1 (branched chain amino acid transaminase 1)
Diseases named in the same sentence as BCAT1 in open-access papers (continued):
Sharing a sentence is not in itself a finding about the gene and the disease.
cancer (continued). "Both the frequency of detection and the amount of methylated BCAT1 and/or IKZF1 DNA released into blood increased with cancer stage." (PMID 25928810, 2015). "We determined that less than 8% of positive control plasma specimens are found to contain at least 20 pg of methylated BCAT1 or IKZF1 DNA, while 63–77% of early stage cancers had 20 pg or more." (PMID 25928810, 2015). "By fitting models of cancer classification (controls, early or late cancer), we show the potential of using the level of methylated BCAT1 and/or IKZF1 DNA in blood to estimate the probability of a positive result being due to the presence of cancer." (PMID 25928810, 2015). "BCAT1 inhibitors represent a potential class of therapeutic agents for cancers; however, none have yet progressed to clinical development." (PMID 40005214, 2025). "The dependency on the two BCAT isoenzymes, BCAT1 and BCAT2, differs across cancers." (PMID 40438606, 2025). "Additionally, cancer metabolism-related genes, including PFKM, IDH3G, PYCR1, and BCAT1, were strongly elevated in expression in response to increased LINC00473 levels." (PMID 38512964, 2024). "Based on the available studies, the enzymes involved in the catabolism of BCAAs, such as BCAT1, BCAT2, and BCKDK, could be potential therapeutic targets for cancer treatment." (PMID 37637065, 2023). "The increased expression of BCAT1 and MFTHD2 might be due to the reduced editing levels of hsa-mir-376a-1_49_A_g and hsa-mir-376c_48_A_g in many cancers." (PMID 37704698, 2023). "BCAT1 overexpression results in increased BCAA catabolism in cancer and is upregulated by several molecules (e.g., hypoxia-inducible factor 1, SMAD5, cMyc, Musashi2) although some cancers favor the reverse reaction." (PMID 37755304, 2023). "The positive correlations of DOT1L with BCAT1 (Pearson correlation γ was 0.5202; p < 0.01) and LDHA with BCAT1 (Pearson correlation γ was 0.5202; p < 0.01) were analyzed from gene expression profiles of 549 GBM cases of the Cancer Genome Atlas (TCGA) database, respectively." (PMID 37298317, 2023). "Nevertheless, the comprehensive potential mechanism and clinical significance of BCAT1 in pan‐cancer have not previously been reported, and more efforts are needed to address this lack." (PMID 34984849, 2022). "Although BCAT1 has been identified as playing an important role in a variety of tumors, no studies on BCAT1 in pan‐cancer have previously been reported." (PMID 34984849, 2022). "Studies have reported that BCAT1 was overexpressed in UC and has implications for the regulation of amino acid metabolism in urinary bladder urothelial cancer (UBUC), which is extremely important for the proliferation, spread and invasion of cancer cells." (PMID 36119495, 2022). "Importantly, BCAT1, EGFR and JAK2 are required for cell proliferation signaling in cancer cells or preadipocytes." (PMID 35269469, 2022). "Differential expression of BCAT1 was detected in various cancers, and it was relevant to some DNA methyltransferases expression, immune checkpoint genes expression, MMR genes expression, MSI, TMB, and neoantigens count in some cancers." (PMID 34984849, 2022). "A recent study reveals that BCAT1 was involved in BCAA metabolism loopholes in connective tissue PDACs that were synthetically lethal and cancer-destructive when co-targeting the matrix-BCAT1 and cancer branched-chain alpha-keto acid dehydrogenase (BCKDH) complexes sexual assault." (PMID 36119495, 2022). "Notably, high BCAT1 expression inversely correlates with survival only in AML patients whose cancers were wild-type for TET2 and IDH, consistent with BCAT1 overexpression promoting tumorigenesis via suppression of TET2 function." (PMID 34109280, 2021). "The results showed that BCAT1, LY6D, and ITGB6 were significantly overexpressed in cancer tissues." (PMID 34976806, 2021).
cancer (continued). "In addition, BCAA metabolic enzymes, such as the cytosolic branched-chain aminotransferase 1 (BCAT1) and mitochondrial branched-chain aminotransferase 2 (BCAT2), have emerged as useful prognostic cancer markers." (PMID 33790982, 2021). "Importantly, in 2017, BCAT1 was proved to be highly expressed in CML, and it facilitated cancer progression." (PMID 32238881, 2020). "In human AML stem cells, BCAT1 is overexpressed, and the BCAA pathway is activated by the low levels of α-KG, displaying a DNA hypermethylation phenotype similar to IDH mutant-positive cancers." (PMID 33511116, 2020). "Significant methylation of either BCAT1 or IKZF1 was seen in 86/91 (94.5%) cancer tissues, with levels independent of stage and higher than that observed in adjacent non-neoplastic specimens (P < 0.001)." (PMID 29796114, 2018). "In some cases, activated macrophages and cancer cells even exploit the same regulatory mechanisms to reach their goals, as was shown, e.g, for the switch to PKM2, stabilization of HIF-1α, or expression of BCAT1." (PMID 29502308, 2018). "Data for BCAT1 and IKZF1 cancer and normal subjects have been published elsewhere." (PMID 27983717, 2016). "Sensitivity of the methylated BCAT1/IKZF1 blood test for recurrence was 75.0% in patients with stage II cancer at diagnosis (6/8), 70.6% of the stage III cancers (12/17), and 33.3% of the stage IV cancers (1/3)." (PMID 27726312, 2016). "We modelled the relationship between disease severity (non-cancer, early stage cancer and late stage cancer) and the fraction of methylated BCAT1 and IKZF1 DNA." (PMID 26445409, 2015). "BCAT1 has been previously identified as one of the c-Myc target genes in different cancers; however, the c-Myc-BCAT1 link has been not studied in EOC." (PMID 26372729, 2015). "Additionally, investigating the interplay between BCAT1 and the immune microenvironment in KIRC could provide deeper insights into its role in cancer progression." (PMID 39324007, 2024). "Quantitative RT–PCR (qRT-PCR) further showed that Bcat1 (related to BCAA metabolism) or Hoxa9, Ccnt1, Pbx1, Rora and Pbx3 (related to transcriptional misregulation in cancer) were significantly reduced in P2x1-null LICs, suggesting that these genes may act as downstream targets of P2X1." (PMID 36418376, 2023). "A prospective correlative biomarker study between presence of methylated BCAT1 and IKZF1 in tissue and blood was conducted in cases with CRC to explore how detection of such ctDNA biomarkers relates to cancer characteristics, methylation in tissue and surgical resection of the primary cancer." (PMID 29796114, 2018). "Consistent with this notion, we identified a subset of this signature containing DPP4, BCAT1, CNTNAP4 and CDH3, whose expression are either the same or increased in CRPC compared to primary PC, and whose gene alterations correlate with a more rapid onset of cancer." (PMID 28055971, 2017). "Moreover, our functional analyses are strongly indicative for evident oncogenic capacity of BCAT1 in EOC, including its potential implication in EOC cell proliferation, cell cycle control and cell migration/invasion, in concordance with similar findings about the role of BCAT1 in other cancers." (PMID 26372729, 2015). "In fact, the first enzymes in the branched-chain amino acids catabolic pathway in the cytosol and mitochondria (BCAT1 and BCAT2; Section 9.2.3) are overexpressed in several cancers." (PMID 37627015, 2023). "Although branched chain amino acid transaminase 1 (BCAT1) has been identified to play an essential role in multiple tumors, no studies on its role in pan‐cancer have been consulted before." (PMID 34984849, 2022). "The presence of methylated BCAT1 and IKZF1 DNA in blood is not likely to be limited to CRC only 24, 35, and as reported here, three of six cases diagnosed with other cancers were positive with the BCAT1/IKZF1 test." (PMID 27726312, 2016).
cancer (continued). "Unfortunately, we could not assess whether detectability of methylated BCAT1 and IKZF1 DNA in blood was associated with appearance of vasculature-related features, as these variables were not recorded in the histological reports for the cancers included in the dataset herein." (PMID 25928810, 2015). "Furthermore, immunostaining showed that both BCAT1 and BCAT2 were highly expressed in cancer cells when comparing noncancerous cholangiocytes (FS1 is a representative case)." (PMID 37076565, 2023).
adenocarcinoma (3 papers, 2024). A common cancer characterized by the presence of malignant glandular cells. "Based on the analysis of BCAT1 immunostaining, we subdivided 72 lung primary adenocarcinoma samples into a high BCAT1 expression group (including 38 cases) and a low expression group (including 34 cases)." (PMID 38993559, 2024).
infection (1 paper, 2024). The state of being infected such as from the introduction of a foreign agent such as serum, vaccine, antigenic substance or organism. "We first overexpressed BCAT1 in PC3 and DU145 cells by lentiviral infection." (PMID 38369471, 2024).
movement disorder (1 paper, 2021). Neurological conditions resulting in abnormal voluntary or involuntary movement, which may impact the speed, fluency, quality and ease of movement. "We recently linked branched-chain amino acid transferase 1 (BCAT1) dysfunction with the movement disorder Parkinson’s disease (PD), and found that RNAi-mediated knockdown of neuronal bcat-1 in C. elegans causes abnormal spasm-like ‘curling’ behavior with age." (PMID 33589689, 2021).
neurodegenerative disease (1 paper, 2022). A disorder of the central nervous system characterized by gradual and progressive loss of neural tissue and neurologic function. "Here were focus on the impact of bcat-1 on the regulation of neuronal function and its role in neurodegenerative disease." (PMID 35228596, 2022).
BCAT1 also shares sentences with these, for which no sentence is quoted: endometrial cancer (3 papers); anaplastic large cell lymphoma (2); invasive carcinoma (2); malignant glioma (2); myeloid neoplasm (2); pancreatic adenocarcinoma (2); renal cell carcinoma (2); systemic lupus erythematosus (2); Abdominal obesity (1); acute leukemia (1); acute lymphoblastic leukemia (1); Alpha-thalassemia (1); anaplastic astrocytoma (1); angioimmunoblastic T-cell lymphoma (1); astrocytoma (1); atrial fibrillation (1); bacterial infection (1); bladder cancer (1); brain tumors (1); cancer of the brain (1); childhood asthma (1); cholangiocarcinoma (1); chronic kidney disease (1); clear cell renal cell carcinoma (1); colorectal tumours (1); cutaneous squamous cell carcinoma (1); esophagogastric adenocarcinomas (1); gallbladder cancer (1); glaucoma (1); gynecological cancers (1).
A further 28 diseases each share a sentence with BCAT1 in 1 paper.